CCL3 (C-C motif chemokine ligand 3)
Diseases named in the same sentence as CCL3 in open-access papers (continued):
Sharing a sentence is not in itself a finding about the gene and the disease.
prostatitis (9 papers, 2013 to 2024). An infectious or non-infectious inflammatory process affecting the prostate gland. "Previous reports have found that the levels of some molecules associated with pain conditions, including CCL3, IL-1B, TNF-α, brain-derived neurotrophic factor (BDNF), and substance P, are increased in the spinal cord of prostatitis animal models." (PMID 31653262, 2019). "C57BL/6 mice received 5 mg/kg body weight of 1-adrenergic or 2-adrenergic receptor agonists intraperitoneally for five days and developed chronic prostatitis, characterized by increased pro-inflammatory cytokines TNF, IL-6, and chemokines CCL2, CCL3." (PMID 37228599, 2023). "In prostate disease BPH, macrophage-secreted CCL3 was downstream target of androgen receptor (AR), which is also secreted by macrophages, to promote prostate stromal cell proliferation." (PMID 29769604, 2018). "The chemokine MIP-1α/CCL3 has inflammatory properties, and elevated blood levels have been reported in chronic widespread pain (mainly FM), lumbar intervertebral disk degeneration, migraine, and prostatitis pelvic pain." (PMID 38304854, 2024). "CCL2 and CCL3 expression levels have been found to be altered in prostatitis, although they are not necessarily markers." (PMID 37228599, 2023). "Moreover, recent studies have identified CCL2 and CCL3 as significant biomarkers for inflammatory IIIA and non-inflammatory IIIB chronic pelvic pain symptoms, underscoring their potential clinical significance in the diagnosis and management of prostatitis." (PMID 37228599, 2023).
SARS-CoV infection (9 papers, 2008 to 2023). "In a MERS-CoV infection, the epithelial and endothelial cells induced significant but delayed IFN and pro-inflammatory cytokine (IL-1β, IL-6 and IL-8) responses, while a large quantity of CCL3, CCL5, CCL2, and CXCL10 was produced during a SARS-CoV infection." (PMID 36016187, 2022). "SARS-CoV infection of myeloid dendritic cells, even unproductive, leads to chemokines upregulation of CXCL10 (IP-10), CCL2 (MCP-1), CCL3 (MIP-1a) and CCL5 (RANTES)." (PMID 32962761, 2020). "Immune cell—recruiting chemokines and cytokines, such as IP-10/CXCL-10, MCP-1/CCL-2, MIP-1α/CCL-3, RANTES/CCL-5, can be strongly induced by MERS-CoV, showing higher inducibility in human monocyte—derived macrophages by MERS-CoV as compared to than SARS-CoV infection." (PMID 32522207, 2020).
gastric cancer (8 papers, 2007 to 2025). A primary or metastatic malignant neoplasm involving the stomach. "In the intestinal type and diffuse type of gastric cancer, the expression of 28 chemokines with their receptors such as CCL3 and CCL8 and 21 interleukins such as IL7 and IL16 demonstrated significantly statistical difference." (PMID 33426088, 2020). "CCL3 and CCL20-recruited DCs modified by adenovirus-trasnsduced, tumor-associated antigen, MAGE-1, can stimulate anti-tumor immunity specific to gastric cancer ex vivo and in vivo." (PMID 20420712, 2010). "In a study investigating gastric cancer, researchers observed that blocking the activator receptor of MCs significantly inhibited the enrichment of MC cells and downregulated the chemokines CCL2/CCL3 in macrophages, resulting in a reduction in gastric cancer cell levels." (PMID 39456702, 2024). "Furthermore, these CCL3 and CCL20-recruited DCs, when modified with tumor antigen gene MAGE-1, could induce not only an effective CTL response against gastric cancer cells ex vivo but also therapeutic, anti-tumor immunity in both subcutaneous tumor and pulmonary metastatic tumor models." (PMID 20420712, 2010). "IL8, CXCL9/MIG, CCL3/MIP-1α, CCL20/MIP-3α, PDGFR-B and TIMP1 plasma levels were significantly different between the non-malignant group and the gastric cancer group." (PMID 21092330, 2010). "CCL20/MIP-3α, TIMP1, IL8, PDGFR-B, CCL3/MIP-1α and CXCL9/MIG were significantly elevated in the plasma from the gastric cancer patients compared to the plasma from individuals with no visible upper gastro-intestinal pathology or those with benign lesions in stomach." (PMID 21092330, 2010). "In addition, median plasma levels of IL8, CXCL9/MIG, CCL3/MIP-1α, CCL20/MIP-3α, PDGFR-B and TIMP1 proteins were significantly different between the non-malignant group and the gastric cancer group." (PMID 21092330, 2010). "In addition, we have shown some of the proteins (CCL20/MIP-3α, TIMP1, IL8, PDGFR-B, CCL3/MIP-1α and CXCL9/MIG) to be detected at a higher level in the plasma from gastric cancer patients than in patients with non-malignant gastric conditions or with normal gastric mucosa." (PMID 21092330, 2010).
lupus (8 papers, 2014 to 2025). "Macrophage inflammatory protein-1 alpha (MIP-1α), also known as CCL3, plays a significant role in the recruitment of immune cells and the inflammation associated with lupus oral lesions." (PMID 40791585, 2025). "While it was unexpected to detect the regulation of a protein involved in megakaryocyte maturation, thrombopoietin has previously been shown to be elevated in systemic lupus erythematosus and where it was strongly correlated with and likely induced by CCL3." (PMID 33246483, 2020). "Non-classical monocytes were observed to preferentially produce TNF and CCL3 in serum from individuals with lupus." (PMID 27097224, 2016). "Previous studies have shown that Fli-1 is a positive regulator of CCL2, CCL3, CCL4, CCL5, CXCL9, and CXCL10 in the kidneys of Fli-1 heterozygote knockout mice with lupus and CXCL5 in dermal small vessels from Fli-1 knockout mice." (PMID 40305194, 2025). "CCL2, CCL3, CCL5, CXCL10, and CXCL16 are increased in lupus nephritis patients and lupus-prone MRL.Faslpr mice." (PMID 37567910, 2023). "We found that expression of CCL2, CCL3, CCL4, CCL5, CCL8, CCL19, and CXCL10 increased 1.6–5.6-fold in the kidney of lupus-prone MRL.Faslpr mice with advancing age from 9 to 16 weeks." (PMID 37567910, 2023). "We also found that expression of CCL2, CCL3, CCL4, CCL5, CCL8, CCL19, and CXCL10 increased 1.6–5.6-fold in the kidney of lupus-prone MRL.Faslpr mice with advancing age from 9 to 16 weeks." (PMID 37567910, 2023). "For example, secretion levels of CCL2, CCL3, CCL4, CCL5, CCL19, CXCL10, and CXCL12 are increased in the kidney of lupus-prone mice and SLE patients during the development of nephritis." (PMID 37567910, 2023). "In lupus-prone NZB/W F1 mice, T cells and monocytes expressing CCR1 and CCR5 migrate to the kidney via sensing CCL3, CCL4, and CCL520." (PMID 37567910, 2023). "The chemokines CCL2, CCL3, CCL5, CXCL10, CXCL12, CXCL13, and CX3CL1 are expressed in the nephritic kidney of lupus-prone mice and SLE patients and increase inflammatory cell infiltration into the kidney." (PMID 30057623, 2018).
neuropathy (8 papers, 2014 to 2025). A disorder affecting the nervous system that manifests with pain, tingling, numbness, and/or muscle weakness. "The differential effects of CCR1 versus CCR5 activation, as well as the potential impact on opioid analgesia, underscore the complex role of CCL3 in neuropathy." (PMID 41153795, 2025). "Overall, based on the findings of these studies the role of CCL3 in directly driving the pain symptoms of neuropathy is confirmed again." (PMID 41153795, 2025). "According to the studies, CCL3 can induce neuropathy by sensitization of TRPV1, P2X7R, or heterologous desensitization of the opioid receptors." (PMID 41153795, 2025). "Neutralizing CCL3 prevented and reversed neuropathy, indicating its involvement in both mechanical allodynia development and maintenance." (PMID 41153795, 2025). "In the present study, we investigated the role of CC-chemokine ligand 3 (CCL3) in the spinal cord in the development and maintenance of mechanical allodynia using a rat model of paclitaxel-induced neuropathy." (PMID 25127716, 2014). "It is feasible that this upregulation of CCL3 in the spinal cord can lead to neuropathy or could drive its development." (PMID 41153795, 2025). "The exact mechanism by which CCL3 could drive the development of neuropathy (and CIPN within that) is not fully understood." (PMID 41153795, 2025). "Thus, the aim of the present study was to investigate the role of spinal CCL3 in mechanical allodynia using a rat model of paclitaxel-induced neuropathy." (PMID 25127716, 2014). "Importantly, it is postulated that autoantibodies against CCL3 are biomarkers of type 1 diabetes development; therefore, research on the impact of the modulation of this chemokine on the development of neuropathy should undoubtedly be continued due to its potential therapeutic benefits." (PMID 37570736, 2023). "Importantly, although after nerve damage caused by CCI, the spinal mRNA level of CCL3 is highly upregulated from the 2nd until the 28th day, its protein level is only changed between the 2nd and 7th days, suggesting the importance of CCL3 in the initial and middle phases of neuropathy." (PMID 37570736, 2023). "Lidocaine treatment reduced neuropathy symptoms by inhibiting HMGB1 and modulating the CCL3/CCR1/CCR5 axis." (PMID 41153795, 2025). "Our research results show that among the MIP-1 family members, CCL3 and CCL9 play important roles in nociceptive pain transmission in neuropathy." (PMID 37190544, 2023). "Our research emphasizes the important function of CCL3 and CCL9 and their receptors in the pathology of neuropathy and suggest their crucial role in opioid analgesia." (PMID 37190544, 2023). "A blockade of the CCL3-CCL4-CCL5/CCR5 axis with maraviroc, a CCR5 antagonist, also reduces NP symptoms by inhibiting the expression of CCL3, CCL4 and CCL5 and intensifies morphine and buprenorphine analgesia in the CCI neuropathy model." (PMID 35330149, 2022). "Clinical studies analyzing the levels of different chemokines in the body fluids of patients with NP have shown that neuropathy increases the concentration of CX3CL1, CXCL5, CXCL10, CCL8, or CCL11 in cerebrospinal fluid (CSF), CCL2, CCL3, CCL4, CCL19 in plasma, and CCL3, CCL4 in saliva." (PMID 35330149, 2022). "Notably, the neutralization of CCL3 reduces pain-like behavior development in STZ-, paclitaxel-, CCI-, and PSNL-induced neuropathy in mice, which may indicate its significant role in this pathology." (PMID 37570736, 2023). "Moreover, similar to CCL3, CCL9 seems to play an important role in the initial phase of neuropathy." (PMID 36611891, 2022).
oral squamous cell carcinoma (8 papers, 2017 to 2023). "CCL3 has been reported to be upregulated in various types of cancers, including chondrosarcoma, non-small cell lung cancer, and oral squamous cell carcinoma, and functions as an oncogene." (PMID 34732692, 2021). "In C57BL/6 (wild type-wt) mice with chemically induced oral squamous cell carcinoma, the expression of both CCL3 and CCR5 increased, and suppression of CCL3 was shown to reduce the proliferation of tumor cells." (PMID 33981848, 2021). "In oral squamous cell carcinoma, the mean survival rate for patients with high numbers of CCL3-positive cells in the tumor parenchyma was shorter than that of the patients with low numbers of CCL3-positive cells, although not significantly." (PMID 32457351, 2020). "CCL3 and CCL4 are considered potential biomarkers of oral squamous cell carcinoma, and they are also related to monocyte aggregation and inflammatory infiltration, but there are few studies on their relationship with oral flora." (PMID 37957648, 2023). "In addition, Da reported that CCL3 and CCR5 showed high expression in oral squamous cell carcinoma, while normal oral epithelial cells also expressed CCL3." (PMID 35935327, 2022). "The expression of CCL3 and its receptors CCR1 and CCR5 was demonstrated in oral squamous cell carcinoma (OSCC), but their role was not defined." (PMID 28881626, 2017).
parasitemia (8 papers, 2020 to 2023). "In agreement with this idea, mice deficient in CCR2, CCR5, CXCL9, CCL3, and CCL2 developed increased parasitemia and/or heart parasitism, whereas higher mortality was also observed in infected CCR5 and CCL2 KO mice." (PMID 37662946, 2023). "During acute infection, CCL3-chemokine KO mice express increased parasitemia and heart parasitism, indicating that early CCL3-mediated recruitment of immune cells to the heart protects against parasite infection." (PMID 37662946, 2023). "During L. monocytogenes infection, CCL2 levels were higher and increased already at d1 post infection (p.i.), while CCL3 levels were lower than during parasitic infection or in naïve mice." (PMID 36010615, 2022). "We found a significant increase in CCL2 levels at d3, and an increase in CCL3 levels at d3 and d5 following parasitic infection." (PMID 36010615, 2022). "Compared with the wild-type counterparts, the increased parasitemia and heart parasitism in acutely T. cruzi-infected ccl3−/− mice supports the premise that CCL3 controls acute infection elicited by diverse pathogens and in different target tissues." (PMID 32194558, 2020). "Together, these data support that CCL3 is important for macrophage control of parasite infection and formation of an IFNγ-triggered TNF- and NO-enriched inflammatory milieu." (PMID 32194558, 2020). "Our work shows that CCL3 deficiency did not impact parasitemia control and survival, as ccl3−/− mice survived acute phase when challenged with low inoculum (100 parasites) of the Colombian strain and developed the chronic infection." (PMID 32194558, 2020). "Serum levels of IL-6, IL-27, CCL3, CCL5, CXCL10, CCL11, and CCL17 in patients with different parasitic infection profiles living in the rural community of Brejo do Amparo, Januária, Minas Gerais, Brazil." (PMID 33777015, 2021). "Although ccl3−/− mice showed higher number of circulating parasites in the early acute infection (28 dpi), independently of the CCL3 status all infected mice controlled the parasitemia and achieved the chronic phase of infection." (PMID 32194558, 2020).
prostate carcinoma (8 papers, 2015 to 2025). A carcinoma that arises from epithelial cells of the prostate gland. "Furthermore, prostate cancer cooperates with tumor-associated fibroblasts to collapse PLZF that occurred by CCL3 derived from the tumor-associated fibroblasts." (PMID 32349303, 2020). "Collectively, these results indicate that CCL3 secreted by fibroblasts co-cultured with prostate cancer cells inhibits tumor suppressor PLZF expression in prostate cancer." (PMID 32349303, 2020). "As a result, we found that tumor-induced impetus stimulated fibroblasts to produce CCL3, which promoted prostate cancer growth and metastasis through the reduction of PLZF/tyrosine phosphatase SHP-1." (PMID 32349303, 2020). "By studying the PLZF/SHP-1/STAT3 signaling pathway involved in CCL3-induced malignancy, we may find a potential therapeutic target for prostate cancer." (PMID 32349303, 2020). "To our knowledge, we have identified for the first that the CCL3/PLZF/SHP-1/pY-STAT3 signaling cascades may be a target for combating prostate cancer cells." (PMID 32349303, 2020). "Therefore, to investigate whether CCL3 inhibits PLZF-mediated transcription of the SHP-1 gene, prostate cancer cells were treated with a recombinant CCL3." (PMID 32349303, 2020).
sarcoidosis (8 papers, 2005 to 2025). Sarcoidosis is a multisystemic disorder of unknown cause characterized by the formation of immune granulomas in involved organs. "Two studies have found associations between elevated levels of CCL3 or CCL4 protein/cell pellet mRNA expression from BALF in patients with sarcoidosis." (PMID 21463523, 2011). "Likewise, Capelli and colleagues demonstrated higher BALF CCL3 and CCL4 protein levels from sarcoidosis patients (n = 30) as compared to healthy controls (n = 18)." (PMID 21463523, 2011). "BALF CCL3 and CCL4 protein levels measured by enzyme-linked immunosorbent assay (ELISA) were not significantly elevated in patients with sarcoidosis (n = 72) compared with normal healthy controls (n = 8)." (PMID 21463523, 2011). "When comparing to control subjects, the expression levels of CC chemokines CCL3 (P = 0.043), CCL4 (P = 0.034), CCL5 (P < 0.001), and CCL8 (P = 0.031) and CXC chemokines CXCL9 (P < 0.001), CXCL10 (P = 0.002), and CXCL11 (P = 0.008) were found to be elevated in sarcoidosis patients." (PMID 26696750, 2015).
type 1 diabetes (8 papers, 2014 to 2025). "Moreover, auto-antibodies to CCL3 have been proposed as biomarkers for an advancement in human type 1 diabetes." (PMID 37190544, 2023). "It was postulated that autoantibodies against CCL3 are biomarkers of type 1 diabetes development, our results suggest that CCL9 may share this function." (PMID 29593735, 2018). "It was postulated that autoantibodies against CCL3 are biomarkers of type 1 diabetes development." (PMID 29593735, 2018). "Therefore, defining the role of this chemokines seems to be highly important, especially because autoantibodies against CCL3 have been postulated to be a biomarker of type 1 diabetes development in humans." (PMID 29593735, 2018). "A similar behavior was found in a type 1 diabetes model where the monocytes were less strongly attracted by MCP-1 (CCL2) and MIP-1α (CCL3) but stronger to MIP-3β (CCL19)." (PMID 34502120, 2021).
allergic rhinitis (7 papers, 2014 to 2024). Inflammation of the nasal mucous membranes caused by an IgE-mediated response to external allergens. "In this regard, there is a study showing the predictive role of CCL3 as a biochemical marker of type 2 inflammation in allergic rhinitis." (PMID 38793051, 2024). "In their 2020 study, Berghi and colleagues discovered a notable elevation in the average serum CCL3 levels among patients suffering from Allergic Rhinitis (AR), compared to those in control groups." (PMID 37692890, 2023). "The levels of CCL3 were significantly higher in patients with seasonal allergic rhinitis than in patients with perennial allergic rhinitis and healthy controls." (PMID 32461855, 2020). "Nevertheless, higher CCL3 concentration in serum could be observed in patients with allergic rhinitis, only seen for the samples overexpressing CST1." (PMID 38270326, 2024). "AR: Allergic rhinitis; CCL3: Chemokine ligand 3; t: Student t-test; df: Degrees of freedom." (PMID 32461855, 2020).
atopic dermatitis (7 papers, 2006 to 2025). "The reported list of inflammatory mediators found in atopic dermatitis includes S100A7, S100A8 S100A9, CCL2, CCL3, IL36A, IL36G, and IL36RN." (PMID 34925353, 2021). "A number of chemokines [CCL2, CCL3, CLL4, CCL8, CCL13, CCL19, chemokine (C-X-C motif) ligand (CXCL) 1, CXCL6, CXCL16] were upregulated in sensitized dogs after allergen challenge, similar to what is observed in human atopic dermatitis." (PMID 25098772, 2014).
chronic lymphocytic leukemia (7 papers, 2016 to 2023). "A high plasma level of CCL3 was associated with poor survival rate in chronic lymphocytic leukemia and diffuse-large B-cell lymphoma." (PMID 32457351, 2020). "Chronic lymphocytic leukemia (CLL) patients contain elevated plasma CCL3 and CCL4 levels." (PMID 28036258, 2017). "The expression of CCL3 and CCL4 is increased in chronic lymphocytic leukemia, and can be used as biomarkers in the therapy targeting chronic lymphocytic leukemia." (PMID 36639681, 2023). "Moreover, elevated CCL3 and CCL4 plasma levels represent independent prognostic markers in chronic lymphocytic leukemia (CLL) patients." (PMID 28036258, 2017).